NLRP7 (NLR family pyrin domain containing 7)
Description:
Inhibits CASP1/caspase-1-dependent IL1B secretion.
Synonyms: NALP7; NOD12; PYPAF3; PAN7; CLR19.4; HYDM; OZEMA25
Tractability: PROTAC: ubiquitination databases record sites on it.
Gene: Protein-coding gene on chromosome 19 (54,923,509 to 54,966,312, reverse strand). Ensembl gene ENSG00000167634.
Subcellular location: Cytoplasm, cell cortex
Subcellular location (Human Protein Atlas): Golgi apparatus
Gene Ontology:
Molecular function: aspartic-type endopeptidase inhibitor activity; caspase binding; interleukin-1 binding
Biological process: cellular response to interleukin-1; cellular response to lipopolysaccharide; negative regulation of cytokine production involved in inflammatory response; negative regulation of interleukin-1 beta production; negative regulation of protein processing; establishment of spindle localization; positive regulation of embryonic development; regulation of inflammatory response
Cellular component: cell cortex; cytoplasm; subcortical maternal complex
Genetic constraint (gnomAD): Loss-of-function variants: 68 observed, 86.78 expected, observed/expected ratio (o/e) 0.78, 90% interval 0.64 to 0.96. The upper end of that interval is the gene's LOEUF score, 0.96, which puts it in group 4 of 6, group 1 being the genes least tolerant of losing a copy. Missense variants: 1,230 observed, 1,249.9 expected, observed/expected ratio (o/e) 0.98, 90% interval 0.94 to 1.03. Synonymous variants: 547 observed, 516.69 expected, observed/expected ratio (o/e) 1.06, 90% interval 0.99 to 1.14.
Homologues: Orthologues: chimpanzee NLRP7 (98% identical), macaque NLRP7 (89% identical). Paralogues in human: NLRP2 (63% identical), NLRP11 (27% identical), NLRP14 (27% identical), NLRP13 (25% identical), NLRP3 (25% identical), NLRP5 (25% identical), NLRP12 (25% identical), NLRP1 (22% identical), NLRP4 (22% identical), NLRP8 (22% identical), NLRP9 (20% identical), NLRC3 (18% identical), and 8 more.
Diseases named in the same sentence as NLRP7 in open-access papers:
NLRP7 is named in the same sentence as 55 diseases in open-access papers, as found by Europe PMC text mining. Sharing a sentence is not in itself a finding about the gene and the disease. The quoted sentences say what the papers report.
hydatidiform mole (39 papers, 2009 to 2025). A gestational trophoblastic disorder characterized by marked enlargement of the chorionic villi, hyperplasia of the villous trophoblastic cells and hydropic changes. "Among all genes present in the database, the largest number of variants corresponded to NLRP7; however, all of these variants were discovered in a single study devoted to mutations in this gene leading to hydatidiform mole or spontaneous abortions." (PMID 40625169, 2025). "Since the first report of a mutation in the gene encoding NLRP7 being linked to the human disease hydatidiform mole in 1999,70 more than 200 unique sequence variants of NLRP7 associated with this condition have now been identified." (PMID 39351983, 2025). "Note that a mutation in Nlrp7 gene found in peripheral blood mononuclear cells from hydatidiform mole patients has been strongly associated with a reduced secretion of IL-1β upon LPS treatment, which was not the case in healthy individual cells." (PMID 38644450, 2024). "It has been reported that mutations occurring in Nlrp7 gene are associated with hydatidiform mole, a gestational trophoblastic disease that develops during the early stage of pregnancy and is responsible for a nonviable fetus." (PMID 38644450, 2024). "NLRP7 mutation leads to recurrent hydatidiform moles in humans, and NLRP7 protein is mainly located in ovine ovarian follicles and in in vitro preimplantation embryos, which plays an important role in ovine reproduction." (PMID 37228386, 2023). "Previous studies identified NLRP7 as a maternal effect gene causing recurrent hydatidiform mole and various forms of reproductive wastage when mutated." (PMID 34068021, 2021). "NLRP7 mutations/variants are responsible for hydatidiform mole formation and are associated with imprinting disorders." (PMID 34068021, 2021). "NLRP7 has extensively been studied in relation to the female reproductive system, as its recessive mutations are associated with recurrent hydatidiform moles (HM)." (PMID 34203890, 2021). "NLRP7 is also mutated in women suffering from hydatidiform moles, a pregnancy outcome with paternalization of imprinting." (PMID 31466347, 2019). "The pathogenesis of familial, biparental hydatidiform moles is caused by the inactivating mutations of NLRP7 and KHDC3L, genes involved in imprinting and inflammation." (PMID 31658584, 2019). "In humans, the primary presentation of NLRP2 maternal effect mutations, is a Beckwith-Wiedemann phenotype in offspring, whereas mutations in NLRP7 cause recurrent biparental hydatidiform moles, a placental developmental phenotype." (PMID 28317850, 2017). "Mutations and genetic variants of NLRP7 have been found in women with infertility associated conditions, such as recurrent hydatidiform mole, recurrent miscarriage, and preeclampsia." (PMID 28810880, 2017). "In 2006, the NLRP7 gene was also identified as a maternal locus associated with recurrent hydatidiform mole (HM), recurrent miscarriage (RM), and recurrent preeclampsia." (PMID 28810880, 2017). "Familial recurrent hydatidiform mole (RHM) is a maternal-effect autosomal recessive disorder usually associated with mutations of the NLRP7 gene." (PMID 26544189, 2015). "NLRP7 is a maternal effect gene as maternal mutations in this gene cause recurrent hydatidiform moles, spontaneous abortions and stillbirths, whereas live births are very rare." (PMID 24130816, 2013). "Homozygous inactivating mutations in NLRP7 in women have been associated previously with abnormal imprinting and recurrent hydatidiform moles." (PMID 19300480, 2009). "Germline NLRP7 mutations are associated with familial recurrent biparental complete hydatidiform mole (FHM) in which there is epigenetic abnormalities at DMRs in multiple imprinting regions." (PMID 19300480, 2009).
hydatidiform mole (continued). "Interestingly, these loss-of-function mutations that lead to hydatidiform mole phenotypes are mainly located within the LRR domain of Nlrp7 gene, which suggests that LRR play a central role in NLRP7 inflammasome activation." (PMID 38644450, 2024). "Mutation of NLRP7 is often associated with human recurrent hydatidiform moles." (PMID 31505467, 2019). "Absence of maternal imprinting of gene expression in hydatidiform moles has also been observed in the rare biparental hydatidiform moles due to NLRP7 (NLR family pyrin domain containing 7) or KHDC3L (KH domain containing 3 like) mutations, suggesting a common endpoint of pathogenesis." (PMID 31658584, 2019). "Mutations in NLRP7 also contribute to the development of hydatidiform mole in abnormal human pregnancies, which may involve inflammation-dependent or independent functions." (PMID 29211899, 2018). "Mutations in the maternal effect gene NLRP7 cause biparental hydatidiform mole (HYDM1)." (PMID 26121690, 2015). "Although there is currently no clear evidence implicating NLRP2 in trophoblast development, mutations of NLRP7 have been reported to cause recurrent hydatidiform moles, an abnormality of pregnancy that is characterized by hypertrophic vesicular trophoblasts in human." (PMID 25889179, 2015). "Indeed, mutations in the NLR gene NLRP7 has been described as a causative hallmark for recurrent hydatidiform moles (RHM) and reproductive loss." (PMID 24681825, 2014). "Further investigation of NLRP7's structural polymorphisms may highlight its participation in the pathogenesis of hydatiform mole, rendering it a possible prenatal marker in the future." (PMID 22110509, 2011). "The patients studied had a history of at least two episodes of a hydatidiform mole, and the impact of the NLRP7 and KHDC3L genes was clarified." (PMID 41011032, 2025). "Genetic investigations suggest that recessive maternal-effect mutations in NLRP7 and KHDC3L genes, leading to abnormal methylation processes in maternally imprinted genes, can contribute to the recurrence of hydatidiform moles." (PMID 39057130, 2024). "Approximately 50 mutations of the NLRP7 gene, and around 10–14% involving KHDC3L, are implicated in the development of hydatidiform moles." (PMID 39057130, 2024). "Mutations in two other members of the SCMC complex, NLRP7 and KHDC3L, contribute to 60% of the clinically recurrent hydatidiform moles." (PMID 37712067, 2023). "Studies have shown that NLRP7, C6ORF221 and other gene mutations can lead to recurrent hydatidiform mole and oocyte defects." (PMID 35120557, 2022). "NLRP7 is the major gene responsible for recurrent hydatidiform mole (HM), an abnormal pregnancy that can develop into gestational choriocarcinoma (CC)." (PMID 34203890, 2021). "The inflammatory gene NLRP7 is the major gene responsible for recurrent complete hydatidiform moles (CHM), an abnormal pregnancy that can develop into gestational choriocarcinoma (CC)." (PMID 34203890, 2021). "Taken together, our results show that NLRP7 mutant iPSCs can faithfully model complete hydatidiform moles." (PMID 32814763, 2020). "Mutations of other NLRP family genes, such as NLRP7 and NLRP2, in parent’s genome result in familial hydatidiform mole and multisite imprinting disorder, respectively." (PMID 32216802, 2020). "Majority of the studies on NLRP7 were focused on its effects on human recurrent hydatidiform moles and a few on other animals." (PMID 31505467, 2019). "Maternal-effect mutations of other human NLRP genes, NLRP7 and NLRP2, cause familial biparental hydatidiform mole and multilocus imprinting disturbance, respectively." (PMID 26323243, 2015). "NLRP7 is an inflammasome protein, but the mechanism by which NLRP7 dysfunctions lead to complete hydatidiform moles is unknown." (PMID 33535645, 2021).
hydatidiform mole (continued). "Numerous studies have described the involvement of the NLRP7 inflammasome in some obstetrical complications, such as the recurrent hydatidiform mole (a disease characterized by an excessive trophoblastic proliferation without embryonic development), especially those related to mutations of NLRP7." (PMID 34572309, 2021). "This important discovery was followed by the identification of other NLRPs playing roles in inflammatory disorders and of the first maternal-effect gene in humans, NLRP7, which is responsible for an aberrant form of human pregnancy called hydatidiform mole (HM)." (PMID 23970884, 2013). "However, the molecular mechanisms and functional effects of these mutations of NLRP7 in causing hydatidiform mole are not known." (PMID 39351983, 2025). "Similarly, women carrying a MEG mutation (e.g., NLRP5, NLRP7, and PADI6) experience a range of reproductive outcomes, including hydatidiform moles, periods of infertility, reproductive loss, offspring with multi-locus imprinting disorders, and unaffected children." (PMID 32516339, 2020). "Methylation analyses of biparental hydatidiform moles (OMIM #231090) caused by mutations of the maternal effect gene NLRP7 revealed aberrant methylation at multiple imprinted loci, indicating that maternal NLRP7 mutations affect establishment and/or maintenance of methylation imprints." (PMID 24130816, 2013). "The involvement of NLRP2 and NLRP7 in inflammasome inhibition and a connection between their presence among maternal RNAs in oocytes and the formation of hydatiform moles, a form of reproductive failure, further suggest that some NLRs may have roles in both inflammation and reproductive success." (PMID 21362197, 2011). "Whereas, hydatidiform moles show extreme hypomethylation of maternal imprinting marks only, NLRP5 variants cause mosaic hypomethylation affecting both maternal and paternal marks, suggesting that NLRP7 may exert its effect in the oocyte, while NLRP5′s action may be postzygotic." (PMID 31466347, 2019). "Pathological variants of zinc finger protein genes such as ZFP57 and ZNF445 and of genes related to the subcortical maternal complex such as NLRP2, NLRP5, NLRP7, and KHDC3L have been identified in cases of multilocus imprinting disturbances (MLIDs) and recurrent hydatidiform moles (RHMs)." (PMID 35581658, 2022).
choriocarcinoma (6 papers, 2021 to 2023). An aggressive malignant tumor arising from trophoblastic cells. "The clinical relevance of NLRP7 in this rare cancer highlights its potential therapeutic promise as a molecular target to treat resistant gestational choriocarcinoma patients." (PMID 36980199, 2023). "We previously demonstrated that NLRP7 promotes choriocarcinoma growth and that its knockdown suppresses cellular proliferation." (PMID 36980199, 2023). "The clinical relevance of NLRP7 in this rare female reproductive cancer highlights its potential therapeutic promise as a molecular target to treat choriocarcinoma." (PMID 34203890, 2021). "NLRP7 is overexpressed in gestational choriocarcinoma (CC) trophoblast cells and may function in an inflammasome-dependent or independent pathways." (PMID 35836259, 2022). "Recently, we provided evidence of a significant function for NLRP7 in human FGR and described the role of NLRP7 in the development of choriocarcinoma." (PMID 35563719, 2022). "In conclusion, this review summarizes the current knowledge on NLRP7 expression and function in early normal pregnancy, in FGR, and in choriocarcinoma." (PMID 35203462, 2022).
breast carcinoma (3 papers, 2021 to 2024). "In breast cancer, NLRP7 affects tumor progression and metastasis by regulating immune cell infiltration and inflammation." (PMID 39697539, 2024). "In the present study, we discovered 84 autophagy-related genes in macrophages incubated by breast cancer cell-derived exosomes induced by ferroptosis, including NLRP7 and STAT3." (PMID 36949762, 2023). "Furthermore, CASP8 (2%), NLRC4 (1%), NLRP3 (1%), NLRP2 (1%), PLCG1 (1%), NLRP1 (1%), NLRP7 (1%), SCAF11 (1%), GSDMC (1%), and NOD1 (1%) occurred somatic mutations as well as most of them had high frequencies of CNV in breast cancer." (PMID 34589498, 2021).
Infertility (3 papers, 2017 to 2021). "Concerning the involvement of Alu in infertility, it would be of great interest to study the epigenetic status of the Alu that are located in the NLRP7 locus in the oocytes of woman suffering miscarriages, as well as the methylation of Alu in the sperm of men suffering unexplained infertility." (PMID 33725281, 2021).
lung adenocarcinoma (3 papers, 2022 to 2024). A carcinoma that arises from the lung and is characterized by the presence of malignant glandular epithelial cells. "Another comprehensive bioinformatics analysis also performed on lung adenocarcinoma identified a prognostic pyroptosis-related gene signature containing five genes (NLRP7, NLRP1, NLRP2, NOD1, and CASP6)." (PMID 36324154, 2022). "not only constructed a pyroptosis-related prognostic predication model involving 5 PRGs (CASP6, NLRP7, NOD1, NLRP1, and NLRP2) in lung adenocarcinoma, but also established a network of mRNA–miRNA–lncRNA closely relating to PRGs." (PMID 35912258, 2022).
Miscarriage (3 papers, 2017 to 2021). A pregnancy that ends at a stage in which the fetus is incapable of surviving on its own, defined as the spontaneous loss of a fetus before the 22th week of pregnancy. "NLRP7 is usually referred to as a maternal effect gene, whose mutations result in miscarriage, stillbirth, fetal growth restriction, preeclampsia, and imprinting disorders." (PMID 31795138, 2019). "Given that defective decidualization of the endometrium has been implicated in miscarriage and preeclampsia, our immunohistochemistry results show that NLRP7 is expressed in the first trimester endometrium." (PMID 28810880, 2017). "Given defective decidualization has been implicated in miscarriage and preeclampsia, in this study we sought to explore the link between the NLRP7 gene and decidual function using an in vitro decidualization model." (PMID 28810880, 2017). "Given defective decidualization has been implicated in miscarriage as well as preeclampsia, we aimed to explore the link between the NLRP7 gene and decidualization." (PMID 28810880, 2017).
ulcerative colitis (3 papers, 2018 to 2023). An inflammatory bowel disease involving the mucosal surface of the large intestine and rectum. "Furthermore, the p.S361L variant of the NLRP7 gene has been demonstrated to correlate with a significantly increased risk of ulcerative colitis." (PMID 37833958, 2023). "Taken together, both the NLRP12 and NLRP7 signaling pathways can be important components of ulcerative colitis pathogenesis." (PMID 37833958, 2023). "In a new area of research, a correlation between the NLRP7 gene and ulcerative colitis (UC) was recently reported, and NLRP7 expression was found to be upregulated in the intestinal mucosa of patients with inflammatory bowel disease (IBD)." (PMID 33838681, 2021).
bladder cancer (2 papers, 2022). "We found that 53.71% of all bladder cancer samples showed genetic mutations in the TCGA bladder cancer cohort and SCAF11 was the most frequent mutation frequency gene, followed by CASP8 and NLRP7." (PMID 36120583, 2022).
colorectal cancer (2 papers, 2021 to 2023). A primary or metastatic malignant neoplasm that affects the colon or rectum. "Thus, we demonstrated that NLRP7 can promote both tumor progression and tumor-associated macrophage polarization in colorectal cancer." (PMID 33838681, 2021). "A recent study showed that NLRP7 accelerated tumor progression and promote M2 macrophage polarization in colorectal cancer." (PMID 36949762, 2023). "By analyzing clinical samples, we found that NLRP7 protein levels were upregulated in colorectal cancer (CRC)." (PMID 33838681, 2021).
fetal growth restriction (2 papers, 2019 to 2023). A fetus that does not grow beyond the 10th percentile of conventionally accepted weight for gestational age. "It was upregulated in the placenta with fetal growth restriction, suggesting that NLRP7 may be involved in the pathogenesis of fetal growth restriction (FGR)." (PMID 37723567, 2023).
gastric cancer (2 papers, 2023 to 2024). A primary or metastatic malignant neoplasm involving the stomach. "In gastric cancer, NLRP7 expression correlates closely with tumor grading and prognosis, with low levels indicating increased invasiveness and poor outcomes, suggesting its potential as a prognostic marker." (PMID 39697539, 2024). "Meanwhile, the expression of NLRP7 and NLRP6 was greatly attenuated in gastric cancer tissues than controls." (PMID 37595258, 2023).
gestational choriocarcinoma (2 papers, 2021 to 2022). Gestational choriocarcinoma is a gestational trophoblastic tumor (GTT) occurring secondary to pregnancy (ectopic or normal), miscarriage, voluntary termination of pregnancy (VTP) or a hydatidiform mole. "In a study on gestational choriocarcinoma (CC), NLRP7 was categorized as one of the key players in the development of CC." (PMID 36276158, 2022). "Altogether, these studies provide strong evidences of the involvement of high NLRP7 expression in the development of gestational choriocarcinoma." (PMID 34203890, 2021).
inflammatory bowel disease (2 papers, 2018 to 2021). A spectrum of small and large bowel inflammatory diseases of unknown etiology. "Single and combined association analysis of the two protein-altering variants in the NLRP7 gene in 5801 inflammatory bowel disease cases and 7074 population controls." (PMID 29211899, 2018).
melanoma (2 papers, 2019 to 2023). A malignant, usually aggressive tumor composed of atypical, neoplastic melanocytes. "Interestingly, in this study, NLRP7 took the largest coefficient in the pyroptosis‐based model, which was positively correlated with an immune‐inflamed TME in melanoma." (PMID 36151761, 2023). "Accordingly, analysis of anti-PD-1-treated melanoma patients suggested that NLRP6, NLRP7, AIM2, and NLRC4 inflammasomes might contribute to antitumor responses unleashed by checkpoint blockers." (PMID 31085177, 2019).